MARCKS (myristoylated alanine rich protein kinase C substrate)
Description:
Membrane-associated protein that plays a role in the structural modulation of the actin cytoskeleton, chemotaxis, motility, cell adhesion, phagocytosis, and exocytosis through lipid sequestering and/or protein docking to membranes. Thus, exerts an influence on a plethora of physiological processes, such as embryonic development, tissue regeneration, neuronal plasticity, and inflammation. Sequesters phosphatidylinositol 4,5-bisphosphate (PIP2) at lipid rafts in the plasma membrane of quiescent cells, an action reversed by protein kinase C, ultimately inhibiting exocytosis. During inflammation, promotes the migration and adhesion of inflammatory cells and the secretion of cytokines such as tumor necrosis factor (TNF), particularly in macrophages. Plays an essential role in bacteria-induced intracellular reactive oxygen species (ROS) formation in the monocytic cell type. Participates in the regulation of neurite initiation and outgrowth by interacting with components of cellular machinery including CDC42 that regulates cell shape and process extension through modulation of the cytoskeleton (By similarity). Plays also a role in axon development by mediating docking and fusion of RAB10-positive vesicles with the plasma membrane (By similarity).
Synonyms: PKCSL; MACS; PRKCSL; 80K-L
Tractability: Antibody: UniProt places it where antibodies can reach, with high confidence; its Gene Ontology location is reachable by antibodies, with high confidence; the Human Protein Atlas places it where antibodies can reach. PROTAC: ubiquitination databases record sites on it; its protein half-life has been measured. Other modalities: a drug acting on it is in phase 2 or 3 trials.
Gene: Protein-coding gene on chromosome 6 (113,857,345 to 113,863,475, forward strand). Ensembl gene ENSG00000277443.
Subcellular location: Cell membrane; Cytoplasm, cytoskeleton; Cytoplasm
Subcellular location (Human Protein Atlas): Plasma membrane; Cytosol; Nucleoplasm; Primary cilium
Pathways (Reactome):
Metabolism: Acetylcholine regulates insulin secretion
Gene Ontology:
Molecular function: actin filament binding; calmodulin binding; identical protein binding; protein kinase C binding
Biological process: actin filament organization; central nervous system development; actin crosslink formation; actin filament bundle assembly; apoptotic process; mitochondrion organization; neural tube development; neurogenesis; response to endoplasmic reticulum stress
Cellular component: cytoplasm; extracellular exosome; focal adhesion; plasma membrane; actin cytoskeleton; actin filament bundle; cell cortex; centrosome; cytoskeleton; germinal vesicle; membrane; organelle
Genetic constraint (gnomAD): Loss-of-function variants: 5 observed, 4.49 expected, observed/expected ratio (o/e) 1.11, 90% interval 0.56 to 1.86. That is too few expected variants to judge how well the gene tolerates losing a copy. Missense variants: 636 observed, 330.66 expected, observed/expected ratio (o/e) 1.92, 90% interval 1.79 to 1.99. Synonymous variants: 289 observed, 170.56 expected, observed/expected ratio (o/e) 1.69, 90% interval 1.54 to 1.87.
Homologues: Orthologues: chimpanzee MARCKS (99% identical), macaque MARCKS (99% identical), rabbit MARCKS (92% identical), pig MARCKS (91% identical), dog MARCKS (71% identical), mouse Marcks (70% identical), rat Marcks (70% identical), tropical clawed frog marcks (51% identical), zebrafish marcksa (40% identical). Paralogues in human: MARCKSL1 (26% identical).
Diseases named in the same sentence as MARCKS in open-access papers:
MARCKS is named in the same sentence as 121 diseases in open-access papers, as found by Europe PMC text mining. Sharing a sentence is not in itself a finding about the gene and the disease. The quoted sentences say what the papers report.
breast cancer (33 papers, 2015 to 2026). A primary or metastatic malignant neoplasm involving the breast. "Although MARCKS activation has been implicated in the aggressive behavior of certain breast cancer subtypes, including inflammatory breast cancer (IBC), its complex formation with HER2 had not been previously identified." (PMID 40940979, 2025). "In breast cancer, MARCKS was reported to be implicated in tamoxifen-resistant MCF7 (Michigan Cancer Foundation-7) breast cancer cells and its inhibition decreased cell motility." (PMID 29295532, 2017). "miR-23b-3p in BM–MSC-derived EVs contribute to the dormant state of breast cancer cells by downregulating a target gene, myristoylated alanine-rich C-kinase substrate (MARCKS), which encodes a protein that promotes cell cycling a motility." (PMID 29238879, 2017). "Conversely, reduction of phospho-MARCKS increased susceptibility of breast cancer cells to paclitaxel, while having a modest effect on the susceptibility to other chemotherapeutics." (PMID 26015406, 2015). "Consistent with other cancers, elevated phospho-MARCKS was associated with metastatic potential of breast cancer." (PMID 26015406, 2015). "The invasion and wound healing assays revealed an association between increased invasiveness and motility of breast cancer cells and up-regulation of MARCKS phosphorylation at the Ser159 and Ser163 sites." (PMID 26015406, 2015). "We next asked if elevated phospho-MARCKS abundance is associated with decreased breast cancer cell survival in response to chemotherapy." (PMID 26015406, 2015). "The results suggest that high phospho-MARCKS abundance caused by paclitaxel contributes to the resistance to paclitaxel in breast cancer cells." (PMID 26015406, 2015). "To ascertain whether phospho-MARCKS is associated with invasive/metastatic potential of breast cancer, we then validated the phospho-MARCKS signal abundance in another cohort of patients (n = 50) with various types of breast tumors, including primary and lymph node metastatic tumors." (PMID 26015406, 2015). "Together, these results indicate that MARCKS functions as a novel HER2-interacting protein that contributes to key cellular phenotypes such as proliferation in HER2-positive breast cancer cells." (PMID 40940979, 2025). "Taken together, these data highlight the potential clinical relevance of MARCKS in HER2-positive breast cancer, but larger, well-stratified studies will be necessary to validate its prognostic and therapeutic implications more robustly." (PMID 40940979, 2025). "To corroborate the direct interaction observed in vitro, we also evaluated the co-localization of HER2 and MARCKS proteins in HER2 3+ human breast cancer specimens (Case 1 and Case 2) by immunohistochemistry." (PMID 40940979, 2025). "BM-MSCs-derived EVs promote a dormant phenotype in metastatic breast cancer cells via the miR-23b/myristoylated alanine-rich C-kinase substrate (MARCKS) axis and Wnt-β-catenin signaling-mediated dedifferentiation." (PMID 40676710, 2025). "It has been reported that miR-23b is enriched in MSC-exosomes and can promote dormancy in metastatic breast cancer cells by decreasing MARCKS expression." (PMID 38250549, 2023). "Again, BMMSC-EVs containing miR-23b promoted dormancy in metastatic breast cancer cells by targeting MARCKS (Myristoylated alanine-rich C-kinase substrate)." (PMID 35915054, 2022). "MARCKS is upregulated in oxaliplatin-resistant pancreatic cancer cells and tamoxifen-resistant breast cancer cells compared to cells sensitive to those therapies." (PMID 36230850, 2022). "Within solid cancers, MARCKS has commonly been identified with a cancer-promoting role in breast cancer, lung cancer, melanoma, glioma, renal cell carcinoma, and liver cancer." (PMID 33958003, 2021).
breast cancer (continued). "EV-miR-23b from BMSCs reduces the proliferation, sensitivity to docetaxel and CD44, a stem cell marker, of bone marrow–metastatic breast cancer (BC) cells by targeting MARCKS, thereby contributing to dormancy of BC stem cells in metastatic niches." (PMID 32503543, 2020). "Bone marrow mesenchymal stem cells secrete miR-23b-containing exosomes, which induce breast cancer dormancy by targeting a cell cycle regulator myristoylated alanine rich protein kinase C substrate (MARCKS)." (PMID 30348200, 2018). "More frequent IHC staining for phospho-MARCKS was found in breast cancer than in normal breast tissue and correlated with unfavorable prognostic parameters and metastatic status." (PMID 29295532, 2017). "Altogether, these studies suggested critical roles of MARCKS in the regulation of breast cancer aggressiveness, and therapeutic resistance, notably to hormone therapy and chemotherapy." (PMID 28009981, 2017). "BM-MSCs transfer miR-23b-containing EVs into breast cancer cells and modulate the dormant state by targeting myristoylated alanine-rich C-kinase substrate (MARCKS), which modulates cell motility and cell cycle progression." (PMID 27582126, 2017). "We first validated the MARCKS antibody using western blot analysis on three breast cancer cell lines with known MARCKS mRNA expression." (PMID 29295532, 2017). "More recently, the unfavorable prognostic impact of high MARCKS mRNA expression on patients’ survival was found in a large annotated database of breast cancer patient samples." (PMID 28009981, 2017). "Before analysis of tissue samples, we validated the MARCKS antibody using western blot analysis on three breast cancer cell lines with known mRNA expression." (PMID 28009981, 2017). "In this situation, miR-23b in EVs from BM-MSCs promoted dormancy through the downregulation of MARCKS, which is a target gene of miR-23b in breast cancer cells." (PMID 26861408, 2016). "To investigate the role of phospho-MARCKS (Ser159/163) in breast cancer, we evaluated phospho-MARCKS abundance by IHC analysis in primary tumor tissue sections from 21 patients with breast carcinomas." (PMID 26015406, 2015). "Altogether, our results supported a critical role for phospho-MARCKS in mediating breast cancer cell invasion and migration." (PMID 26015406, 2015). "Since chemotherapy has been used to treat all stages of breast cancer, particularly MBCs, we examined the effect of chemotherapy treatment on phospho-MARCKS abundance." (PMID 26015406, 2015). "Our studies point to the critical role of phospho-MARCKS in the unresponsiveness of breast cancer to taxanes and suggest that phospho-MARCKS is a druggable target to overcome resistance to paclitaxel." (PMID 26015406, 2015). "Collectively, these results demonstrate critical roles of phospho-MARCKS in the regulation of breast cancer malignancy and paclitaxel resistance." (PMID 26015406, 2015). "We then uncovered that down-regulation of phospho-MARCKS was able to reduce intravasation of cancer cells, microvessel density and angiogenic factors, hallmarks of metastatic development of breast cancer, in our xenograft model." (PMID 26015406, 2015). "Among multiple chemotherapeutic agents used in treatment of breast cancers, only mitotic inhibitors increased phospho-MARCKS abundance." (PMID 26015406, 2015). "Lastly, knockdown of MARCKS or pharmacologic agents reduced paclitaxel-induced phospho-MARCKS and improved responsiveness of breast cancer cells to paclitaxel, both in vitro and in vivo." (PMID 26015406, 2015). "First, phospho-MARCKS in breast cancer acts upstream Src activation, which has been documented in the regulation of paclitaxel resistance." (PMID 26015406, 2015). "Western blots demonstrated that both phospho-MARCKS and MARCKS expressions were higher in the invasive breast cancer cell lines, MDA-MB-231 and MDA-MB-468." (PMID 26015406, 2015).
breast cancer (continued). "Here, we showed that MANS peptide attenuates the effect of paclitaxel-induced phospho-MARCKS and enhances the paclitaxel sensitivity of breast cancer." (PMID 26015406, 2015). "Among chemotherapeutic agents, mitotic inhibitors, including paclitaxel, vincristine or eribulin, notably promoted phospho-MARCKS accumulation in multiple breast cancer cells." (PMID 26015406, 2015). "Our data suggest that unresponsiveness of breast cancer to paclitaxel treatment is, at least in part, mediated by phospho-MARCKS and also provide an alternative therapeutic strategy against breast cancer by improving taxanes sensitivity." (PMID 26015406, 2015). "Second, phospho-MARCKS abundance accumulated in response to the treatment of breast cancer cells with mitotic inhibitors, particularly paclitaxel." (PMID 26015406, 2015). "To further validate the role of phospho-MARCKS in conveying paclitaxel resistance in breast cancer cells, we performed a dose-course analysis of MDA-MB-468 cells undergoing paclitaxel treatment." (PMID 26015406, 2015). "Herein, we investigated how phospho-MARCKS is regulated in breast carcinoma, and its role in the context of chemotherapy." (PMID 26015406, 2015). "TCGA analysis further revealed that high MARCKS expression significantly correlates with ER negativity, as confirmed by multivariate analysis, suggesting its potential role as a prognostic indicator in aggressive breast cancer subtypes." (PMID 40940979, 2025). "MARCKS also modulates PI3K/AKT and MAPK signaling pathways, which are critical for cancer cell survival and proliferation, and have been implicated in aggressive breast cancer subtypes." (PMID 40940979, 2025). "MARCKS from plasma extracellular vesicles is also considered to diagnose breast cancer." (PMID 35980268, 2022). "Recently, some studies showed that as a proto-oncogene, MARCKS takes part in the tumorigenesis and development of several cancers such as lung cancer, breast cancer, renal cell carcinoma, pancreatic cancer, and HCC and plays an important role in participation in signaling pathways of many cancers." (PMID 35401213, 2022). "Extensive data suggest that dysregulated MARCKS expression drives the development and progression of several solid tumors including melanoma, glioma, renal cell carcinoma, lung cancer, colorectal cancer, liver cancer, and breast cancer." (PMID 33958003, 2021). "In small series of 21 and 50 breast tumors, including a majority of cancers, the authors showed frequent high IHC staining for phospho-MARCKS in breast cancer as compared to adjacent normal breast tissue and correlation with poor differentiation/high grade and metastatic status." (PMID 28009981, 2017). "There was high heterogeneity between breast cancers with respect to MARCKS staining." (PMID 28009981, 2017). "The other study on MARCKS and breast cancer was recently published." (PMID 28009981, 2017). "We found heterogeneous MARCKS staining between all breast cancers." (PMID 28009981, 2017). "MSC-derived EVs from breast cancer cells contain over expressed miR-23b, which promotes dormancy in metastatic breast cancer cells through the suppression of myristoylated alanine-rich C-kinase substrate (MARCKS) gene." (PMID 29657282, 2017). "Therefore, transfer of miR-23b by EVs and its suppression of MARCKS, one of the mechanisms for cancer recurrence, result in the suppression of the cell cycle and the transition to dormancy in breast cancer cells." (PMID 26861408, 2016). "Decreases MARCKS expression and promotes breast cancer cell dormancy in the metastatic niche." (PMID 27517627, 2016). "Importantly, it is plausible that phospho-MARCKS serves as an informative biomarker and druggable target for paclitaxel resistance in breast cancer." (PMID 26015406, 2015). "We next assessed phospho-MARCKS and total MARCKS abundance in some breast cancer cell lines." (PMID 26015406, 2015).
breast cancer (continued). "Particularly, a known phospho-MARCKS inhibitor, MANS peptide, was demonstrated to increase paclitaxel efficacy and attenuate angiogenesis/metastasis of xenografted breast cancer cells by decreasing abundance of phospho-MARCKS and messages of inflammatory mediators." (PMID 26015406, 2015). "However, the regulation of phospho-MARCKS abundance and its functional consequence in breast cancer are yet to be elucidated." (PMID 26015406, 2015). "To explore whether MARCKS inhibition interferes with the angiogenic activity of breast cancer, we examined the expression of several angiogenic factors after knockdown of MARCKS." (PMID 26015406, 2015). "To determine whether an increase in phospho-MARCKS or total MARCKS abundance promotes breast cancer cell invasiveness and motility, we used a MARCKS-specific short hairpin RNA (MARCKS-shRNA) to deplete endogenous MARCKS, then followed by re-expression of wild-type or S159/163A-MARCKS." (PMID 26015406, 2015). "To directly confirm the interaction between HER2 and MARCKS, we first performed a proximity ligation assay (PLA) using the HER2-positive breast cancer cell line SK-BR-3." (PMID 40940979, 2025). "Previously, we observed the overexpression of MARCKS in two PAC-resistant ovarian cancer cell lines, and the role of MARCKS in PAC resistance has been reported in breast cancer." (PMID 35628654, 2022). "Through the combination treatment of breast cancer using MANS peptide and paclitaxel, we confirmed that MANS peptide has an inhibitory effect on paclitaxel-enhanced MARCKS phosphorylation, as PKC inhibitor did." (PMID 26015406, 2015). "MARCKS was more commonly found in breast cancers that do not respond to hormone therapy, suggesting its potential as a prognostic marker for aggressive tumors." (PMID 40940979, 2025). "In addition, treatment of breast cancer xenografts with MANS peptide sensitizes cancer cells to paclitaxel and decreases angiogenesis/metastasis of cancer cells by reducing phospho-MARCKS levels." (PMID 36230850, 2022). "In our larger series, we confirmed the poor-prognosis value of MARCKS expression in breast cancer in univariate but not in multivariate analysis." (PMID 28009981, 2017). "The strengths of our study include the number of cases tested with a total of 502 breast cancers including 133 IBC, a tumor rare but aggressive; to our knowledge, it is the first study analyzing specifically MARCKS protein expression in IBC and the largest one in breast cancer." (PMID 28009981, 2017). "In a screen of patients with breast tumors, we find that the abundance of phospho-MARCKS, not MARCKS protein per se, increased in breast cancers and positively correlated with tumor grade and metastatic status." (PMID 26015406, 2015). "In breast cancer cells, using stable isotope labeling by amino acids in cell culture (SILAC), SK1 has been shown to interact with key proteins that regulate cell motility (supervillin), cell adhesion and migration (myristoylated alanine-rich C-kinase substrate (MARCKS)-related protein)." (PMID 34043703, 2021). "Exosomal miR-23b was reported to transit from bone marrow mesenchymal stem cells (BM-MSCs) to metastatic breast cancer cells which were homing to bone marrow (BM2), and the BM2 cells could be induced to enter into dormancy by inhibiting myristoylated alanine-rich C kinase substrate (MARCKS)." (PMID 31395836, 2019). "Molecular profiling of experimental models with and without MARCKS activation could provide relevant insight about the regulation and the consequences of MARCKS expression in breast cancer." (PMID 28009981, 2017). "In the literature, inhibition of MARCKS using MPS (MARCKS phosphorylation site domain) peptide showed promising results in different cancers with inhibition of tumor growth and metastases in vivo, but no study was reported in breast cancer." (PMID 36139501, 2022).